BIN1 (bridging integrator 1)
Diseases named in the same sentence as BIN1 in open-access papers (continued):
Sharing a sentence is not in itself a finding about the gene and the disease.
prostate carcinoma (9 papers, 2007 to 2023). A carcinoma that arises from epithelial cells of the prostate gland. "A reduced expression of Bin1 caused by DNA methylation, has been reported in breast and prostate cancers." (PMID 28152502, 2017). "Genetic causes of BIN1 inactivation in prostate cancer mostly occur as a result of allelic losses." (PMID 17477881, 2007). "BIN1 CpG island cancer related methylation in breast and prostate cancers was confirmed by bisulphite sequencing and its methylation frequency was evaluated by methylation sensitive PCR." (PMID 17477881, 2007). "Complete or partial losses of BIN1 contained in this region in breast and prostate cancers have been reported." (PMID 17477881, 2007). "This suggestion is supported by the study of genes reactivation after treatment of prostate cancer cell lines with 5-aza-2'-deoxycytidine, in which reactivation of BIN1 was detected in the DU145 cells." (PMID 17477881, 2007). "One of these is BIN1 mRNA aberrant splicing detected in melanoma and prostate cancer." (PMID 17477881, 2007). "BIN1 re-expression in the DU145 prostate cancer cell line after 5-aza-2'-deoxycytidine treatment was recently reported but no methylation of the BIN1 promoter CpG island was found in DU145." (PMID 17477881, 2007). "One possibility, which was never tested, is that BIN1 is downregulated in BC by alternative splicing like it is in prostate cancer and melanoma." (PMID 17477881, 2007). "In addition, GST pull-down assays of DU145 prostate cancer cells using individual GST-fused domains of BIN1 and PARP1 showed BIN1 bound to the automodification domain of PARP1 through the BIN-amphiphysin-Rvs-related (BAR-C) domain of BIN1." (PMID 22778941, 2012).
Arrhythmia (8 papers, 2010 to 2025). Any cardiac rhythm other than the normal sinus rhythm. "Administration of augmented ventricular pacing to mice carrying heterozygous and homozygous deletions of BIN1 showed a higher prevalence of VF and VT arrhythmias compared with the control wild-type group, with a more severe VT being attributed to mice bearing the homozygous deletion of BIN1." (PMID 39769189, 2024). "In addition to skeletal muscle defects, both patients have mild mental retardation and the more severely affected male also displays abnormal ventilation and cardiac arrhythmia, thus expanding the phenotypic spectrum of BIN1-related CNM to non skeletal muscle defects." (PMID 21129173, 2010). "Testosterone, plasma bridging integrator 1, soluble ST2, miRNAs, anti-DSG2 antibodies, correlate with disease severity and arrhythmias incidence." (PMID 34206637, 2021).
melanoma (8 papers, 2007 to 2022). A malignant, usually aggressive tumor composed of atypical, neoplastic melanocytes. "It has been found that these brain specific isoforms have been found in certain melanomas and the BIN1 isoform is spliced to contain these exons in these melanomas, resulting in the loss of tumor suppressor activity." (PMID 33946706, 2021). "QKI-5 in BEAS2B cells induced the exclusion of BIN1 exon12A, which has been shown to abolish its binding to c-Myc and lose its anti-oncogenic activity in melanoma cells." (PMID 24722255, 2014).
congenital myopathy (7 papers, 2013 to 2026). "Autosomal recessive BIN1 mutations are reported to cause infantile or childhood onset, usually slowly progressive, congenital myopathy." (PMID 32456280, 2020). "This differs from the defects of calcium handling already shown in other congenital myopathies including disorders linked to BIN1, RYR1 or MTM1 mutations that are centered on defects of triad membrane components, i.e. T-tubules and SR." (PMID 27870637, 2016). "Type 1 myofiber predominance is also observed in other triadopathies, including RYR1, DNM2, BIN1 and MTM1-associated congenital myopathies." (PMID 39209426, 2024). "A specific phenotype of autosomal recessive BIN1-related congenital myopathy has been reported in Spanish Roma patients, harboring the p.Arg234Cys founder mutation either in homozygosity or rarely in compound heterozygosity with the p.Arg145Cys variant." (PMID 32456280, 2020). "We sought for dog breeds with molecularly unsolved congenital myopathies and we identified the canine Inherited Myopathy of Great Danes as a disease model reproducing the histological and physiological defects observed in BIN1-related CNM patients." (PMID 23754947, 2013).
amyloid (6 papers, 2019 to 2024). "In conclusion, our results show an association between BIN1 rs744373 risk-allele carriage and in vivo assessed tau pathology in elderly subjects with and without amyloid pathology." (PMID 30992433, 2019). "Hence, RIN3 may act as a scaffold between CD2AP and BIN1: promoting amyloid pathology via CD2AP and enhancing tau pathology via BIN1." (PMID 35359443, 2022).
pancreatic cancer (6 papers, 2022 to 2025). "In pancreatic cancer, BIN1 acts as a macrophage phenotype switching associated gene and serves as an independent risk indicator for prognosis." (PMID 40016843, 2025). "In pancreatic cancer, BIN1 protein levels are markedly downregulated and inversely correlated with UBE2O expression." (PMID 40426910, 2025). "In conclusion, UBE2O drives pancreatic cancer progression by driving the ubiquitin-dependent degradation of BIN1 and thereby activating c-Myc-driven oncogenic pathways." (PMID 40426910, 2025). "For instance, hsa_circ_0057104, an alternative splicing isoform of PDHK1, modulates the miR-628-3p/BPTF axis and degrades BIN1, thereby enhancing the growth, metastasis, and glycolysis of pancreatic cancer cells." (PMID 38360682, 2024). "CircPDK1 also serves as a skeleton to strengthen the contact of ubiquitin-conjugating enzyme E2O (UBE2O) with bridging integrator 1 (BIN1), causing UBE2O-mediated degradation of BIN1 and accelerating the advancement of pancreatic cancer." (PMID 37532687, 2023).
esophageal squamous cell carcinoma (5 papers, 2017 to 2023). Esophageal squamous cell carcinoma (ESCC) is a type of esophageal carcinoma (EC) that can affect any part of the esophagus, but is usually located in the upper or middle third. "There has been evidence in experimental studies that hypermethylation of the Bin1 gene (also reduced expression identified in breast cancer tissues) is associated with poor prognosis in esophageal squamous cell carcinoma (ESCC) patients." (PMID 31323834, 2019). "Another study indicated that BIN1 overexpression could restrain esophageal squamous cell carcinoma tumorigenesis." (PMID 36475339, 2023). "Since our previous study revealed that BIN1 suppressed EMT in esophageal squamous cell carcinoma (ESCC), we then verified whether the SNHG10/miR-200a-3p axis affected EMT-related proteins by regulating BIN1 in A2780 and SKOV3 cells." (PMID 35149697, 2022). "Methylation decreased the expression of bridging integrator-1 (Bin1) in esophageal squamous cell carcinoma, and Bin1 methylation could augment the malignant biological behaviors of esophageal squamous cell carcinoma." (PMID 29651226, 2018). "However, the methylation status of Bin1 and potent biological functions in esophageal squamous cell carcinoma (ESCC) remain unclear." (PMID 28152502, 2017).
glioma (5 papers, 2017 to 2025). A benign or malignant brain and spinal cord tumor that arises from glial cells (astrocytes, oligodendrocytes, ependymal cells). "In glioblastoma (PDC000446), BIN1 emerged as a critical tumor suppressor epigenetically silenced in gliomas." (PMID 40597613, 2025). "Additionally, we assessed in situ hybridizations for TGFBI and BIN1 in glioma tissue sections from IGAP." (PMID 29262845, 2017). "The RNA-binding protein, HNRNPA2B1, can regulate the splicing of many tumor suppressor genes in glioma, such as RON, BIN1, WWOX, and c-FLIP." (PMID 32272554, 2020). "For example, HNRNPA2B1 could enhance the expression of the oncogenic isoforms of many tumor suppressor genes (e.g., RON, BIN1, WWOX, and c-FLIP) in glioma by modulating the splicing of these genes, thereby promoting glioma progression and aggressiveness." (PMID 34745938, 2021).
lung carcinoma (5 papers, 2017 to 2025). "For example, it was reported that the ablation of BIN1 could accelerate the susceptibility to cancer especially lung cancer during aging in humans." (PMID 36475339, 2023). "Kaplan-Meier analysis showed that in stage I/II lung cancer, high BIN1 expression correlated with improved survival compared to low expression." (PMID 40346580, 2025). "To elucidate the clinical significance of BIN1 in lung cancer, we analyzed the correlation between BIN1 expression levels and the prognosis of lung cancer patients using the StarBase2.0 and TIMER2.0 databases, both derived from TCGA data." (PMID 40346580, 2025). "Specifically, 50% of BIN1 chimeric mice developed lung cancer, followed by liver cancer." (PMID 40346580, 2025). "In lung cancer, CDK5 promotes the tumour’s progression by inhibiting the tumour-suppressive function of bridging integrator 1 (BIN1)." (PMID 33396266, 2020). "We observed an increased expression of BIN1 through SRSF1 downregulation by USP15 and USP4 knockdown, which may, in turn, inhibits the metastatic ability of lung cancer cells." (PMID 35027535, 2022).
colon cancer (4 papers, 2009 to 2025). "The association between IDO or Bin1 expression and TNM stages and the 5-year survival rate in colon cancer patients was analyzed." (PMID 19695096, 2009). "Immunohistochemical BIN1 expression is low in colon cancers compared to normal tissue." (PMID 28257124, 2017). "Finally, neither IDO nor Bin1 in primary colon cancers was associated with the 5-year survival rate." (PMID 19695096, 2009). "In primary colon cancer, the strong expression of IDO existed in 9/71 cases (12.7%), while the strong expression of Bin1 existed in 33/71 cases (46.5%)." (PMID 19695096, 2009).
lymph node metastasis (4 papers, 2012 to 2025). "Furthermore, low BIN1 expression was strongly associated with lymph node metastasis and more advanced clinical stages." (PMID 40346580, 2025). "After stepwise multivariate survival analysis, the differentiation grade, TNM stage, lymph node metastasis, Bin1 methylation were observed to be independent prognostic factors for ESCC patients." (PMID 28152502, 2017). "Comparing the lymph node metastasis to the matched normal tissue, the former revealed differentially lower methylation ratio for BIN1, GSTP1 and P14 promoter regions (P < 0.05, P < 0.01, P < 0.05; respectively)." (PMID 22695536, 2012). "Covariates included in the Cox proportional hazards model were gender, age, differentiation grade, invasion range, lymph node metastasis, TNM stage, and Bin1 methylation status." (PMID 28152502, 2017).
type 2 diabetes (4 papers, 2017 to 2025). "Not of statistical significance, APOE ε2 showed a trend to protect against type 2 diabetes (OR = 0.342; p = 0.093), in contrast BIN1 rs744373 risk-allele carriers were more likely to exhibit the disease (OR = 1.491; p = 0.099)." (PMID 39081475, 2022). "Interestingly in a Portuguese primary care-based cohort, BIN1 rs744373 risk-allele carriers were found to have a lower risk of dyslipidemia and respiratory diseases, while tending to have an increased risk of type 2 diabetes." (PMID 41465142, 2025). "In summary, we identified a novel metabolite locus (MOGAT2) in single variant analyses and four genes (GFRAL, BIN1, TFRC, OR51Q1) within gene-based tests and could show that two previously known mGWAS loci (FADS1 and REV3L) might be relevant for the risk of type 2 diabetes." (PMID 28729637, 2017). "While we found that a carbohydrate-rich diet did not negatively impact colon health, or Bin1 immunotherapy response, this diet promotes obesity and type II diabetes and may be less desirable for middle-aged or elderly individuals receiving UC immunotherapy." (PMID 37479833, 2023).
colitis (3 papers, 2019 to 2023). Inflammation of the colon. "Preclinical genetic and pharmacological studies have demonstrated that Bin1 attenuation abolishes sensitivity to experimental chemically-induced colitis in association with an enhancement of intestinal epithelial cell barrier function." (PMID 37479833, 2023). "Specifically, we previously demonstrated that mice treated with the cell-penetrating Bin1 mAb protects against susceptibility to chemically-induced colitis, acting through several mechanisms to pleiotropically block colonic inflammation." (PMID 37479833, 2023). "Our group recently demonstrated that attenuation of BIN1 gene reduced disease severity in a mouse model of experimental colitis occurring in association with an enhancement of epithelial barrier function." (PMID 36322599, 2022). "In our study, we confirmed the presence of microorganisms of these genera in the fecal pellets as well as cultures of DSS-induced colitis mice, with some changes in their levels associated with Bin1 mAb treatment." (PMID 36322599, 2022). "Taken together, these data specified alterations in the gut microbiome that were associated with the healthful benefits of Bin1 mAb treatment in animals subjected to DSS-induced colitis." (PMID 36322599, 2022). "In summary, our study demonstrated that the therapeutic benefits of Bin1 mAb treatment in DSS-induced colitis mice is associated with a preservation of enteric neurons and a rebalancing of the gut microbiome." (PMID 36322599, 2022). "In our study, we observed that induction of DSS-induced colitis was associated with a change in the phenotype of the bacterial population as observed by microscopy, with rebalance of the phenotype in subjects receiving Bin1 mAb treatment." (PMID 36322599, 2022). "Notably, we observed that on the standard diet Bin1 mAb administration increased Ileibacterium (a Bacillota increased by high fat diet) and Turicibacter (a Bacillota associated with colitis), whereas it reduced Dubosilla (a Gram-positive genus reduced by high-fat diets)." (PMID 37479833, 2023). "We determined the changes in the enteric neurons after DSS-induced colitis and during its treatment with Bin1 mAb." (PMID 36322599, 2022). "In this study, the stool of mice before DSS-induced colitis, during DSS-induced colitis and during Bin1 mAb immunotherapy or control treatments was collected for microbiome analysis." (PMID 36322599, 2022). "The morphology of the bacterial cells was similar to the untreated controls demonstrating that Bin1 mAb influences the microbiome during DSS-induced colitis treatment." (PMID 36322599, 2022). "In this paper, we report progress in how Bin1 mAb treatment protects against DSS-induced colitis; specifically, it protects enteric neurons thereby preventing bowel movement dysfunction, and that it promotes formation of a healthy gut microbiome." (PMID 36322599, 2022). "We recently reported the development of a novel colitis therapy using both cell culture and animal models, targeting the Bin1 protein thereby supporting epithelial barrier function." (PMID 36322599, 2022). "Although BIN1 has not yet been implicated in BBB integrity, intestinal barrier tightening has been observed in a mouse model of colonic inflammation treated with a BIN1 monoclonal antibody." (PMID 31159836, 2019). "Based on the study, we explored whether the Bin1 monoclonal antibodies (mAb) developed by our laboratory phenocopied effects of genetic attenuation in the colitis model." (PMID 36322599, 2022). "In our study, we observed that Lactobacillus was totally absent in DSS-induced colitis mice but restored to significant extent by Bin1 mAb treatment." (PMID 36322599, 2022).
glioblastoma (3 papers, 2020 to 2025). The most malignant astrocytic tumor (WHO grade IV). "PREX1 and ABHD2 have also shown to promote tumor invasion and progression in glioblastoma, while the tumor suppressor BIN1 was found to be regulated by HNRNPA2B1, a putative proto-oncogene in GBM." (PMID 32070274, 2020).
Lewy body disease (3 papers, 2020 to 2024). "Interestingly, GBA1, BIN1 and TMEM175, which are associated with case–control Lewy body disease GWAS11, did not appear significant when comparing LBD-D with LBD-ND." (PMID 38978726, 2024).
memory impairment (3 papers, 2019 to 2021). "Our second major finding was that the association between BIN1 rs744373 and memory impairment was mediated via elevated global tau levels." (PMID 30992433, 2019). "Our mediation analysis suggests that the BIN1 rs744373 SNP is linked to memory impairment due to the increase in tau pathology in the BIN1 rs744373 risk-allele carriers." (PMID 30992433, 2019). "For example, the microglia AD genes, including APP, CLU, BACE2, and BIN1, are specifically enriched for other diseases such as neurofibrillary degeneration, Parkinson’s dementia, and aging memory impairment." (PMID 34044854, 2021). "Thus, it is plausible that alteration in neuronal BIN1 expression would lead to an unbalanced hippocampal circuitry resulting in memory impairments." (PMID 31408457, 2019).